FGF21 (fibroblast growth factor 21)
Diseases named in the same sentence as FGF21 in open-access papers (continued):
Sharing a sentence is not in itself a finding about the gene and the disease.
osteoporosis (8 papers, 2020 to 2025). A condition of reduced bone mass, with decreased cortical thickness and a decrease in the number and size of the trabeculae of cancellous bone (but normal chemical composition), resulting in increased fracture incidence. "IVW method showed that there was a genetic causal relationship between FGF21 and osteoporosis, and the overexpression of FGF21 increased the risk of osteoporosis (OR=1.003, 95%CI (1.001-1.005), P=0.004)." (PMID 39296716, 2024). "This suggests FGF21 can decrease the bone mineral density, thus increasing the risk of osteoporosis, which is consistent with the predecessors’ research results." (PMID 39296716, 2024). "In recent years, many observational studies have found that FGF21 is closely related to bone mineral density and osteoporosis, but the causal relationship between them is still unclear." (PMID 39296716, 2024). "Mediation analysis showed that FGF21 was associated with an increased risk of osteoporosis (OR=1.003, 95%CI (1.001-1.005), P=0.0037)." (PMID 39296716, 2024). "The aim of this study was to explore the causal relationship between FGF21 and osteoporosis by two-sample, mediated Mendelian randomization method." (PMID 39296716, 2024). "Of note, our results also indicated that FGF21 was an independent risk factor for osteoporosis in multivariate linear regression analyses." (PMID 34011291, 2021). "Of course, the causative effect of FGF21 on osteoporosis in patients on HD and the exact mechanism of the involvement of FGF21 in the regulation of osteoporosis need to be further confirmed by large-sample RCT studies and related animal and cell experiments." (PMID 34011291, 2021). "Therefore, this study used two-sample, mediated Mendelian randomization (MR) analysis to explore the causal relationship between FGF21 and osteoporosis and bone mineral density." (PMID 39296716, 2024). "Therefore, this study used two-sample, mediated Mendelian randomization (MR) analysis to explore the causal relationship between FGF21 and bone mineral density and osteoporosis, so as to provide reference for the prevention and treatment of osteoporosis." (PMID 39296716, 2024). "Other studies have shown that FGF21 can promote the secretion of hepatic hormone, which binds to osteoclast precursors and promotes osteoclast differentiation, thereby aggravating osteoporosis." (PMID 39296716, 2024). "Our investigations of serum samples from human osteoporosis patients demonstrated that FGF21 levels were elevated in the osteoporosis group." (PMID 39221030, 2024). "In recent years, the relationship between FGF21 and osteoporosis has been continuously explored, and studies have shown that FGF21 is closely related to bone resorption and bone formation." (PMID 39296716, 2024). "Zhou found that FGF21 levels in the liver and plasma were significantly increased in the osteoporosis rat model after ovariectomy." (PMID 39296716, 2024). "Meanwhile, FGF21 (r = -0.136, P < 0.05) and FGF23 (r = -0.151, P < 0.05) were both negatively associated with osteoporosis." (PMID 34011291, 2021). "The area under the curve (AUC) of FGF21 in predicting osteoporosis was 0.71 (95 % CI, 0.64 to 0.78, P < 0.001), with good sensitivity (80.2 %) but low specificity (41.1 %)." (PMID 34011291, 2021). "FGF21 combined with age is a good predictive biomarker for osteoporosis in patients on haemodialysis, especially those with less residual renal function." (PMID 34011291, 2021). "In HD patients with 24-hour urine volume > 100ml, the AUC of FGF21 combined with age in predicting osteoporosis was 0.837 (95 % CI, 0.778 to 0.896, P < 0.001) with better sensitivity (70.1 %) and specificity (81.4 %)." (PMID 34011291, 2021). "In the osteoporosis group, patients on HD had a mean age of 66.45 ± 13.28 years and a median serum FGF21 level of 640.86 pg/ml (interquartile range 1.72, 3176.14)." (PMID 34011291, 2021).
osteoporosis (continued). "In conclusion, elevated FGF21 levels have a positive relationship with the incidence of osteoporosis in patients on HD." (PMID 34011291, 2021). "In the two subgroups based on 24-hour urine volume in HD patients, the area under the curve (AUC) of FGF21 in predicting osteoporosis were 0.657 (95 % CI, 0.558 to 0.755, P = 0.001) and 0.691 (95 % CI, 0.606 to 0.775, P = 0.001), respectively." (PMID 34011291, 2021). "In our osteoporosis group, CT attenuation and Log (FGF21) were normally distributed data and CT attenuation values were also negatively associated with Log (FGF21) (r = -0.238, P = 0.019) in pearson correlation analysis." (PMID 34011291, 2021). "In the present study, we showed that serum FGF21 levels were significantly higher in the osteoporosis group of patients on HD." (PMID 34011291, 2021). "Based on the CT attenuation value, serum FGF21 levels were higher in our osteoporosis group (median 640.86 pg/ml vs. 245.46 pg/ml, P ˂ 0.01)." (PMID 34011291, 2021). "In HD patients with 24-hour urine volume ≤ 100ml, the AUC of FGF21 combined with age in predicting osteoporosis was 0.833 (95 % CI, 0.772 to 0.894, P < 0.001) with good sensitivity (61.8 %) and specificity (90.5 %)." (PMID 34011291, 2021). "In general, either FGF21 alone or combined with age was an effective predictor of osteoporosis in patients on HD, especially those with less RRF." (PMID 34011291, 2021). "In our study, we found that FGF21 had a great value in predicting osteoporosis with a relatively high sensitivity (80.2 %)." (PMID 34011291, 2021). "In the non-osteoporosis group, patients had a mean age of 52.86 ± 14.77 years and a median serum FGF21 level of 245.46 pg/ml (interquartile range 0.95, 1764.29)." (PMID 34011291, 2021). "MR Analysis showed that FGF21 was negatively correlated with Total body bone mineral density, Heel bone mineral density, Forearm bone mineral density, Femoral neck bone mineral density, and positively correlated with osteoporosis (P<0.05)." (PMID 39296716, 2024). "Whether the effects of FGF21 on bone mineral density and osteoporosis are influenced by gender is still controversial, and more studies are needed to clarify." (PMID 39296716, 2024). "Some scholars have found that FGF21 is closely related to bone mineral density and osteoporosis." (PMID 39296716, 2024). "FGF21 has a positive relationship with the incidence of osteoporosis in patients on haemodialysis." (PMID 34011291, 2021). "Notably, the AUC of FGF21 combined with age in predicting osteoporosis increased significantly to 0.829 (95 % CI, 0.78 to 0.88, P < 0.001) with optimal sensitivity (91.4 %) and higher specificity (47.9 %)." (PMID 34011291, 2021). "In addition, FGF21 alone or combined with age can be a predictive biomarker for osteoporosis in patients on HD, especially those with less RRF." (PMID 34011291, 2021). "Furthermore, FGF21 combined with age showed good specificity (90.5 %) and sensitivity (61.8 %) for the prediction of osteoporosis in patients on HD with less residual renal function." (PMID 34011291, 2021). "In this study, we investigated whether FGF21 could serve as a biomarker to predict osteoporosis in a haemodialysis cohort." (PMID 34011291, 2021). "Furthermore, FGF21 combined with age yielded a marked specificity (90.5 %) and sensitivity (61.8 %) in predicting osteoporosis of haemodialysis patients with less residual renal function." (PMID 34011291, 2021). "Since females are at a greater risk for osteoporosis than males, it is possible that a lack of FGF21 response to exercise may be an adaptive mechanism for maintaining bone mass." (PMID 40440637, 2025). "Clinical tiral data revealed that FGF21 analog could lead to osteoporosis complications." (PMID 36967758, 2023). "Moreover, the sensitivity of predicting osteoporosis could rise to 91.4 % when FGF21 was combined with age." (PMID 34011291, 2021). "Moreover, FGF21 (β = -0.067, P < 0.05) was an independent factor for osteoporosis." (PMID 34011291, 2021).
osteoporosis (continued). "To delve deeper into the connection between serum FGF21 levels and bone health, we utilized DXA (dual-energy x-ray absorptiometry), the gold standard for diagnosing osteoporosis, to evaluate various bone-related parameters in these subjects." (PMID 39221030, 2024). "Ultimately, we explored the predictive values of serum FGF21 and FGF23 on osteoporosis in our HD cohort." (PMID 34011291, 2021). "In the present study, we evaluated the relationship between FGF21 and FGF23 and osteoporosis in a population-based retrospective HD cohort." (PMID 34011291, 2021). "Our analysis revealed compelling findings: Individuals with osteoporosis exhibited markedly elevated levels of circulating FGF21 compared to non-osteoporosis subjects." (PMID 39221030, 2024). "Therefore, increased bone-marrow fat and adiponectin, FGF21 levels and decreased BMD in osteoporosis." (PMID 38352899, 2024). "We assessed the correlation of CT attenuation values with serum FGF21 and FGF23 levels and tested whether they were independent factors for osteoporosis." (PMID 34011291, 2021). "ROC curves were constructed to compare the prognostic value of FGF21 and FGF23 for osteoporosis." (PMID 34011291, 2021). "Serum FGF21 levels were significantly higher in the osteoporosis group (P < 0.001), while serum FGF23 levels were not significantly different between these two groups." (PMID 34011291, 2021). "Interestingly, we found that serum FGF21 levels were higher in our osteoporosis group than in the non-osteoporosis group in patients on HD." (PMID 34011291, 2021). "In contrast to FGF21, we observed that FGF23 had no value in predicting osteoporosis, although FGF23 had been proven to play a significant role in bone metabolism." (PMID 34011291, 2021). "First, we compared the serum FGF21 and FGF23 levels in patients on HD with or without osteoporosis on the basis of CT attenuation values." (PMID 34011291, 2021). "A search in PubMed found no relevant information about the levels of FGF21 and IGFBP1 in patients with osteoporosis, and future studies are needed to determine whether either or both of these proteins may be differentially expressed by patients with osteoporosis." (PMID 36967758, 2023).
pancreatic cancer (8 papers, 2018 to 2025). "To elucidate the molecular mechanisms underlying FGF21-mediated suppression of pancreatic cancer progression, we employed an integrated approach combining transcriptomic profiling with computational biology and functional molecular assays." (PMID 41426308, 2025). "Taken together, these results strongly suggest that loss of FGF21 expression may contribute to a more aggressive and metastatic phenotype in pancreatic cancer." (PMID 41426308, 2025). "The correlation between FGF21 expression in human pancreatic cancer tissues and invasion and metastasis." (PMID 41426308, 2025). "Next, the association between FGF19, FGF21, FGFR1, FGFR4, and KLB overexpression and the overall survival of pancreatic cancer patients was evaluated." (PMID 30593273, 2018). "Complementary experimental approaches employing both cell culture systems and animal models will then evaluate whether exogenous FGF21 supplementation inhibits the invasive and metastatic behaviors of pancreatic cancer cells in inflammatory microenvironments." (PMID 41426308, 2025). "FGF21 acts as a downstream metabolic target of oncogenes or as a corrective metabolic suppressor in tumor lesions, with its overexpression antagonizing the development of liver and pancreatic cancers." (PMID 39286013, 2024). "Indeed, while two studies have suggested that FGF21 protect from NASH to HCC transition and development, as well as from prostate and pancreatic cancer development, other studies support an oncogenic role of FGF21 in various other cancers, including thyroid, lung and colorectal cancers." (PMID 35409319, 2022). "Injection of recombinant FGF21 inhibited RAS and attenuated inflammation-driven tumor formation, proposing intervention at the RAS-PPARγ-FGF21 axis as a novel target to treat or prevent pancreatic cancer." (PMID 37686465, 2023). "The pharmacological dosage of FGF21 supplementation effectively inhibited pancreatic intraepithelial neoplasia lesions, inhibited liver metastasis, and prolonged the overall survival of KRAS-mediated pancreatic cancer under the high-fat-diet challenge." (PMID 36263162, 2022). "The circulating levels of FGF21 in pancreatic cancer patients are still unclear, but both pancreatic cancer specimens and cell lines had lower levels of FGF21 than normal human pancreatic tissues and cells, respectively." (PMID 36263162, 2022).
pulmonary hypertension (8 papers, 2021 to 2024). Increased pressure within the pulmonary circulation due to lung or heart disorder. "DIZE and fibroblast growth factor 21 (FGF21) can up‐regulate ACE2 expression to improve pulmonary hypertension and decrease inflammation‐induced endothelial cell injury." (PMID 33443816, 2021). "FGF21 activation of the PPARγ pathway eliminates the production of inflammatory factors, suppresses pulmonary artery smooth muscle cell proliferation, and alleviates pulmonary arterial hypertension." (PMID 38733164, 2024). "Taken together, our results show that FGF21 can improve pulmonary vascular remodelling and collagen deposition by inhibiting the negative regulatory effects of miR‐130 on PPARγ and ultimately alleviating pulmonary hypertension." (PMID 34989130, 2022). "Furthermore, by upregulating PPAR expression and suppressing inflammatory cytokine levels, fibroblast growth factor 21 (FGF-21) reduces pulmonary hypertension and suppressing inflammatory cytokine levels." (PMID 34200791, 2021).
colitis (7 papers, 2017 to 2024). Inflammation of the colon. "In this study, we discovered that FGF21 deficiency protected against DSS-induced colitis through epithelial IL-22-STAT3-mediated signaling." (PMID 37432218, 2023). "We conclude that FGF21 deficiency attenuated the severity of DSS-induced acute colitis, which is likely mediated by enhancing the activation of the IL-22-STAT3 signaling pathway in intestinal epithelial cells." (PMID 37432218, 2023). "Surprisingly, the loss of body weight and the severity of the colitis induced by DSS treatment in WT mice were significantly attenuated in FGF21 KO mice." (PMID 37432218, 2023). "We also observed that the transplantation of colitis-associated dysbiotic microbiota caused a reduced production of FGF21 in the liver of GF recipient mice." (PMID 36735734, 2023). "Here, we demonstrated that FGF21 deficiency attenuated DSS-induced acute colitis in mice." (PMID 37432218, 2023). "Together with the results showing the reduced production of FGF21 and adiponectin, these findings suggest that the disrupted FGF21-adiponectin axis caused by the transplantation of colitis-associated dysbiotic microbiota is due to a lowered SCFA producing capacity of the microbiota." (PMID 36735734, 2023). "Taken together, the transplantation of the colitis-associated dysbiotic microbiota was causally associated with impairment of FGF21-adiponectin axis, leading to metabolic abnormalities, including adipose tissue dysfunctions, dysregulated hepatic lipid metabolism, and reduced insulin sensitivity." (PMID 36735734, 2023). "Additional compelling evidence regarding the role of FGF21 in intestinal inflammation comes from studies in animal models which show that chemically induced colitis is one of the factors stimulating the secretion of FGF21." (PMID 38983722, 2024). "In FGF21 knockout mice, FGF21 depletion attenuated the severity of chemically induced acute colitis by enhancing the activation of the interleukin 22-STAT3 signaling pathway in intestinal epithelial cells." (PMID 38983722, 2024). "As colitis is a systemic inflammatory disease, we examined cytokine levels in the plasma of WT and FGF21 KO mice treated with DSS." (PMID 37432218, 2023). "FGF21 deletion protected mice from DSS-induced acute colitis by increasing IL-22 expression-mediated epithelial STAT3 activation, which decreased intestinal inflammation and maintained intestinal goblet cell and Paneth cell homeostasis." (PMID 37432218, 2023). "It is thus possible that the inflammatory response during colitis-induced FGF21 expression inhibits intestinal HIF1α expression, leading to a decrease in IL-22 and therefore exacerbating the expression of inflammatory IL-6 production." (PMID 37432218, 2023). "Whole-body FGF21 knockout (FGF21 KO) mice and WT control mice were analyzed to determine the role of FGF21 in the development of colitis." (PMID 37432218, 2023). "Recent studies showed that LPS-induced inflammation resulted in the increased expression of FGF21, and colitis patients had higher levels of plasma FGF21." (PMID 37432218, 2023). "DSS-induced colitis mice showed a significant reduction in expression levels of both hepatic FGF21 and skeletal muscle irisin compared to non-colitis control mice." (PMID 33674694, 2021). "In the present study, we analyzed the effect of FGF21 on adipose tissue lipolysis in a murine model of DSS-induced colitis and in 3T3-L1 adipocytes." (PMID 28584524, 2017). "We investigated the impact of FGF21 in experimental colitis-induced epididymal white adipose tissue (eWAT) lipolysis." (PMID 28584524, 2017). "Our results demonstrate that experimental colitis induces eWAT lipolysis via an IL-6/FGF21-mediated signaling pathway." (PMID 28584524, 2017). "Importantly, FGF21 KO mice demonstrated an improved colitis score and reduced myeloperoxidase (MPO) activity compared to the WT mice." (PMID 37432218, 2023).